CCL8 (C-C motif chemokine ligand 8)
Description:
Chemotactic factor that attracts monocytes, lymphocytes, basophils and eosinophils. May play a role in neoplasia and inflammatory host responses. This protein can bind heparin. The processed form MCP-2(6-76) does not show monocyte chemotactic activity, but inhibits the chemotactic effect most predominantly of CCL7, and also of CCL2 and CCL5 and CCL8.
Synonyms: MCP-2; MCP2; SCYA10; SCYA8; HC14
Tractability: Antibody: UniProt places it where antibodies can reach, with medium confidence; UniProt predicts a signal peptide or a membrane-spanning region; its Gene Ontology location is reachable by antibodies, with medium confidence.
Gene: Protein-coding gene on chromosome 17 (34,319,435 to 34,321,402, forward strand). Ensembl gene ENSG00000108700.
Subcellular location: Secreted
Gene Ontology:
Molecular function: phospholipase activator activity; protein binding; protein kinase activity; CCR chemokine receptor binding; chemokine activity
Biological process: calcium ion transport; cell-cell signaling; exocytosis; host-mediated suppression of viral genome replication; intracellular calcium ion homeostasis; antimicrobial humoral immune response mediated by antimicrobial peptide; chemokine-mediated signaling pathway; chemotaxis; eosinophil chemotaxis; inflammatory response; positive regulation of cell migration; response to virus; signal transduction; immune response; negative regulation of leukocyte proliferation; positive regulation of leukocyte migration
Cellular component: extracellular region
Genetic constraint (gnomAD): Loss-of-function variants: 1 observed, 1.75 expected, observed/expected ratio (o/e) 0.57, 90% interval 0.19 to 1.79. That is too few expected variants to judge how well the gene tolerates losing a copy. Missense variants: 105 observed, 99.49 expected, observed/expected ratio (o/e) 1.06, 90% interval 0.9 to 1.24. Synonymous variants: 37 observed, 36.98 expected, observed/expected ratio (o/e) 1, 90% interval 0.77 to 1.32.
Homologues: Orthologues: chimpanzee CCL8 (99% identical), macaque CCL8 (96% identical), pig CCL8 (74% identical), dog CCL8 (71% identical), rat Ccl12 (63% identical), mouse Ccl12 (60% identical), mouse Ccl8 (54% identical), zebrafish cxcl32b.1 (32% identical). Paralogues in human: CCL11 (69% identical), CCL2 (69% identical), CCL7 (65% identical), CCL13 (62% identical), CCL15 (37% identical), CCL16 (37% identical), CCL3L3 (37% identical), CCL4 (36% identical), CCL23 (35% identical), CX3CL1 (35% identical), CCL3 (34% identical), CCL4L2 (33% identical), and 14 more.
Diseases named in the same sentence as CCL8 in open-access papers:
CCL8 is named in the same sentence as 211 diseases in open-access papers, as found by Europe PMC text mining. Sharing a sentence is not in itself a finding about the gene and the disease. The quoted sentences say what the papers report.
COVID-19 (49 papers, 2020 to 2025). A disease caused by infection with severe acute respiratory syndrome coronavirus 2. "Evidence from clinical studies indicates that the severity of COVID-19 is positively associated with chemokine and inflammatory cytokine levels in the plasma of patients, such as TNF-α, IL-1β, IL-6, CCL2, CCL8, and CXCL9." (PMID 38104081, 2023). "Among the modified genes, CCL2, CCL7, and CCL8 were increased in post-COVID-19 monocytes, similar to levels in monocytes from patients with severe acute forms of COVID-19." (PMID 38203577, 2023). "Some COVID-19 convalescent plasma indicated high levels of IgGs to certain chemokines (for example, CCL8, CXCL13 and CXCL16) compared with healthy controls." (PMID 36879067, 2023). "Cytokine IFNA7, as well as chemokines CXCL13, CXCL10, CCL7, and CCL8 were present in the proteins selected for predicting severe COVID-19." (PMID 37069249, 2023). "They identified neutrophils (IFITM2, IFITM1, H3-H3B, SAT1 and S100A8) and macrophage cluster-1 (CCL8, CCL3, CCL2, KLF6 and SPP1) as the main immune cell subsets associated with severe COVID-19 cases." (PMID 34109284, 2021). "Among the identified gene signatures, IFITM2, IFITM1, H3F3B, SAT1, and S100A8 gene signatures were highly associated with neutrophils, while CCL8, CCL3, CCL2, KLF6, and SPP1 were associated with macrophage cluster-1 in severe-COVID-19 patients." (PMID 33138195, 2020). "Similarly, several studies have reported the overexpression of chemokines in COVID-19, such as C-C motif chemokine ligands 8 and 11 (CCL8 and CCL11), and C-X-C motif chemokine ligands 2, 8, 9, and 16 (CXCL2, CXCL8, CXCL9, and CXCL16)." (PMID 40722944, 2025). "Levels of CCL2 and CCL8 in BAL fluid as well as CXCL10 in plasma samples collected during the first 48 hours of intubation were higher in patients with COVID-19 relative to all other groups, with the exception of patients with other viral pneumonias (q < 0.05, Mann-Whitney)." (PMID 38502186, 2024). "In COVID-19 non-survivor genes related to neutrophil chemotaxis and migration, including CXCL10, CCL20, CCL8, C3AR1, CCL2, VAV3 are significantly upregulated; increased neutrophil is a typical signature of COVID-19 and closely linked to fatality, as already reported by other studies." (PMID 37949875, 2023). "Furthermore, genes encoding CCL7, CCL8, and CCL13 were also found in bronchoalveolar lavage (BAL) in patients with COVID-19." (PMID 36851766, 2023). "In line with our findings, CD14hiCD16hi cells and AMs enriched with viral RNA in autopsy lungs of COVID-19 patients also had distinct transcriptomes which were largely recapitulated in what we construe as CXCL10-associated genes (CXCL11, CCL18, CCL8, ISG15, CD83)." (PMID 35483404, 2022). "Of note, Ccl8 and Ccl2 as well as Cxcl9 and Cxcl10, chemoattractants for monocytes and T cells, respectively, were significantly up-regulated in the lungs of AR-infected mice and in COVID-19 patients, in line with the increased recruitment of these cells." (PMID 34812647, 2022). "In addition, CCL2 and CCL8 were found elevated in postmortem lung specimens from COVID-19 patients compared to lung biopsies from healthy controls, thus corroborating the role of the cytokine storm in COVID-19 severity." (PMID 34209845, 2021). "Therefore, anti-CCL8/MCP-2 antibodies might offer a novel point of intervention in the management of patients with COVID-19 induced hyperinflammation." (PMID 34540715, 2021). "In addition, this study analyzed the transcriptome of bronchial epithelial cells and the serum cytokine and chemokine profiles of deceased COVID-19 patients, and confirmed an increase in inflammatory chemokines like IL-6, IL1RA, CCL2 and CCL8, suggesting immunologic misfiring in COVID-19." (PMID 32887790, 2020). "We note the differential expression of many inflammatory CC chemokines (CCLs) in severe COVID-19, including CCL2, CCL3, CCL8, CCL3L1 and CCL7, and CXC chemokines such as CXCL2 and CXCL8." (PMID 39187683, 2024).
COVID-19 (continued). "High levels of these molecules, detected after macrophage treatment with VLPs (TNFα, IL-1β, CCL8, CXCL8, CXCL9, CXCL16, CXCL1, and CXCL2), were shown to correlate with severe COVID-19 in other studies." (PMID 38664730, 2024). "In support of this model, samples collected within 48 hours of intubation from patients with COVID-19 clustered distinctly from other patient groups, driven by CXCL10 and CCL8 in BAL samples and CXCL10 in plasma." (PMID 38502186, 2024). "Among the many cytokines with significantly greater cumulative exposure in COVID-19 were CXCL10, CCL8, CCL2, IL-6, and TNF-α (q < 0.05, Mann-Whitney)." (PMID 38502186, 2024). "Post–COVID-19 MDMs showed higher expression of proinflammatory chemokines (CCL2, CCL8, and CCL7), driving neutrophil recruitment, including in COVID-19." (PMID 36668902, 2023). "In addition, severe COVID-19 patients BAL alveolar macrophages (n = 88) are characterized by a cluster activation, involving genes encoding several pro-inflammatory mediators such as CCL7, CCL8 and CCL13, that can mediate recruitment and activation of monocytes and T cells." (PMID 36941580, 2023). "High-throughput and ultrasensitive proteomics platforms showed that the serum of cytokines and chemokines such as CCL8 and CXCL10 in COVID-19 patients was significantly higher than in healthy controls." (PMID 35747501, 2022). "IL-15, CCL8, and CXCL10 levels were also significantly elevated in the BAL fluid of patients with COVID-19 in the mid- or late phase of a coinfection compared with patients without coinfections." (PMID 34793331, 2022). "The macrophage cluster-1-derived signature (CCL8, CCL3, CCL2, KLF6, and SPP1) was confirmed to be significantly higher in severe cases of COVID-19 compared to control and mild cases." (PMID 33138195, 2020). "Our results showed upregulation of chemotactic factors, including CCL4, CCL8, and CCL11, that all shared CCR5 as their receptor, as a common derangement observed in both diseases; RA and COVID-19." (PMID 32923679, 2020). "Elevated concentrations of CCL2 and CCL8 were also observed in BAL samples from patients with COVID-19, relative to patients with pneumonia secondary to nonviral pathogens (q < 0.05, Mann-Whitney)." (PMID 38502186, 2024). "In BAL fluid, only the levels of CCL8, CXCL10, and CCL7 were significantly lower, and the levels of IL-10 were higher, in patients with COVID-19 after they received corticosteroids compared with those who did not receive corticosteroids (q < 0.05, Mann-Whitney)." (PMID 38502186, 2024). "While some genes involved in monocyte and lymphocyte migration and function were expressed in the COVID-19(+) TV group (CCL13, CCL8, and CCL20), a greater number of these genes were expressed in the COVID-19(-) PU control group (CCL19, CCL18, CXCL13, CCL4, CCL5, CXCL9)." (PMID 37026002, 2023). "Mostly, markers of inflammation such as IL-6, IL-10, CXCL10 (also known as IP10), CXCL11, CCL2, CCL7, CCL8, PD-L1, and IL-18R1 were increased at the early stage of COVID-19 in ICU patients compared to non-ICU ones." (PMID 35269564, 2022). "Our analysis suggests that CCL8, CCL18, and other chemokine receptor binding are enriched in the gene expression profile of patients who suffered COVID-19 and COPD, which may contribute to the high rate of severe illness and mortality." (PMID 35747501, 2022). "In conclusion, our study demonstrates that BLC/CXCL13, sCD30, MCP-2/CCL8 and IP-10/CXCL10 are specifically and individually upregulated in symptomatic COVID-19-positive patients but not in patients suffering from other respiratory infections with similar symptoms." (PMID 34540715, 2021). "In addition to these three markers, the ICU group tend to be separated from non-ICU patients by OSM and S100A12, whereas all COVID-19 patients can be distinguished from healthy controls by CASP8, IFNγ, IL-18R and CCL8." (PMID 33239683, 2020).
COVID-19 (continued). "Conversely, and regardless of vaccination status, antibodies to CCL19, CCL8, CCL13, CCL16, CXCL7 and CX3CL1 significantly increased, those to CXCL17 remained generally stable and those to CCL22 followed variable kinetics at month 12 compared with month 6 in the COVID-19 convalescents." (PMID 36879067, 2023). "Further, IL-4, IL-9, CCL5, CCL8, GM-CSF, and PDGF are exclusively induced by SARS-CoV-2 and these differences may explain why multi-organ injury including testicular damage and long-term sequelae is observed in COVID-19 patients and not with influenza virus." (PMID 37200377, 2023).
breast carcinoma (35 papers, 2015 to 2026). "In human liver metastases of breast cancer, CCL8 expression was also associated with the presence of NETs." (PMID 40796724, 2025). "CCL8 is not only a chemokine associated with breast cancer, but also undergoes expression changes during the process of mammary gland involution, which is a physiological process." (PMID 34160019, 2021). "Several studies have implicated elevated CCL8 in breast cancer progression, metastasis and relapse free survival (RFS)." (PMID 34692697, 2021). "Our data implies loss of CCL3 and CCL8 in breast cancer could lead to enhanced cell proliferation and tumor progression." (PMID 31620367, 2019). "Our data implies loss of CCL3 and CCL8 in breast cancer could lead to enhanced cell proliferation and progression." (PMID 31620367, 2019). "Subsequently, we sought to evaluate the potential anticancer activity of DTCCL8 in breast cancers at which the effect of CCL8 is established." (PMID 40545574, 2025). "Here we report the role of a distinctive subpopulation of KCs, designated by CD62L and CCL8 expression, in liver metastasis of breast cancer." (PMID 40796724, 2025). "Studies have shown that CCL8 promotes breast cancer dissemination, enhances the migration and invasion of esophageal cancer cells and drives lung cancer progression." (PMID 41561540, 2025). "Six of the genes (CASP1, CCL2, ADGRE5, IL3RA, RSPO1, and STAB1) are co‐expressed with the CH25H gene in both cancers, while two genes (ANPEP in breast cancer and CCL8 in prostate cancer) are exclusively co‐expressed with the CH25H gene in one of the tumors." (PMID 41159143, 2025). "Nevertheless, high breast cancer tissue CCL8 mRNA tissue levels have been reported to increase in breast cancers compared to adjacent healthy tissues and to be associated with worse RFS." (PMID 38594742, 2024). "Recent studies revealed that CCL8 recruits monocytes/macrophages into cervical cancer, postpartum breast cancer, or hepatocellular carcinoma." (PMID 37734869, 2023). "In breast cancer, CCL8 was produced by TAMs, was an independent poor prognostic factor, and enhanced cancer cells’ malignancy." (PMID 38136340, 2023). "In breast cancer, CCL8 is produced in stromal fibroblasts at the tumor margins and in tissues in which cancer cells tend to metastasize, such as the lungs and the brain." (PMID 37091868, 2023). "The abundance of CCL8+ TAM infiltrate is similarly increased in human breast cancer patient samples and also correlates with poor survival." (PMID 35362482, 2022). "Chemokine CCL8, which is a member of a conserved chemokine cluster, plays a role in cancer metastasis by modulation of the tumor-promoting activity in breast cancer including recruiting M2 macrophages." (PMID 36072582, 2022). "The ablation of CCL8 in mice implanted with breast cancers reversed the chemoattractant effect of M2 macrophages in a CCR2-dependent manner." (PMID 36532057, 2022). "CCL8 has previously been identified as a prometastatic migration factor in several mouse models, including breast cancer, glioma, and melanoma." (PMID 35362482, 2022). "Recently, one study showed that treating breast cancer with Paclitaxel can increase macrophage chemotactic factors such as CCL8, IL-34, CSF-1, and CSF-1 receptors in vivo to enhance TAM migration." (PMID 34207035, 2021). "Chemokine (C-C motif) Ligand 8 (CCL8), a chemokine produced by TAMs, was found to induce angiogenesis in breast cancer model." (PMID 34207035, 2021). "In this way, CCL8 is a chemoattractant in localizing M2 macrophages with the tumor microenvironment and contributes to the promotion of involution-related breast cancer with its increased expression." (PMID 34160019, 2021). "Previous work has indicated an oncogenic role for CCL8: its expression correlates positively with progression of various cancers, including breast cancer, and with metastasis of cancers to the lung." (PMID 34844613, 2021).
breast carcinoma (continued). "Together, CCL17 and CCL25 in AA breast cancer patients decrease overall survival, while high CCL8 decreases overall survival in CA patients." (PMID 32824813, 2020). "In present literatures, CCL8 is a cytokine that promotes the metastasis in kinds of tumors, including breast cancer, lung cancer and esophageal squamous cell carcinoma." (PMID 32719391, 2020). "We also observed increased expression of CCL8, a chemokine that modulates the migration of immune cells and breast cancer cells." (PMID 31693710, 2019). "Breast cancer TAMs express CCL8, which is chemotactic for monocytes and drives a positive regulatory loop between cancer cells and TAMs through CSF1 and TNF-α, which upregulates SIGLEC1." (PMID 30930117, 2019). "In mouse models, CCL8 has a role in metastasis formation in melanoma and promoted tumor cell invasion and motility in mammary cancer models." (PMID 30930117, 2019). "The identified CCL proteins have various carcinogenetic properties, such as the increase in breast cancer cell proliferation, chemoresistance development and T-cell and NK-cell regulation (CCL8), stimulation of angiogenesis and cancer cell proliferation (CCL23) and control of cell migration (CCL28)." (PMID 38594742, 2024). "Consequently, physiological process, histopathologic evaluation as well as molecular subgroup parameters should be also considered in the analysis and interpretation of CCL8 expression levels in breast cancer." (PMID 34160019, 2021). "Thus, CCL8 contributes to the development of breast cancer by re-shaping the microenvironment with both autocrine and paracrine effects." (PMID 34160019, 2021). "The preservation of the CCL8 chemokine gradient in breast cancer epithelial cells and stroma may be critical in metastasis." (PMID 34160019, 2021). "In addition, higher expression of CCL8 decreases overall survival only in CA breast cancer patients." (PMID 32824813, 2020). "Interestingly, Ccl8 is highly enriched in cluster 6, which has been shown to be an important factor for mammary cancer cell dissemination, suggesting a potential role in tumor cell invasion." (PMID 33072601, 2020). "Interestingly, in mouse models of metastatic breast cancer, CCL8 was also shown to recruit regulatory T cells (Tregs) through CCR5, and that metastasis in this model was reduced by inhibition of this receptor." (PMID 30930117, 2019). "Interestingly, CCL8 has been reported to play a role in the tumor microenvironment by supporting mouse mammary cancer cell dissemination." (PMID 30930117, 2019). "Thus, we further analyzed CCL8 expression patterns in invasive breast cancer samples." (PMID 37884960, 2023). "Gene set variation analysis (GSVA) showed that CCL8 are positively correlated with gene sets related with hypoxia, glycolysis, mTOR, macrophage, M2 macrophage, negatively correlated with glucose starvation, M1 macrophage in invasive breast cancer samples, respectively." (PMID 37884960, 2023). "Also, high CCL8 expression was remarkably associated with negative Progesterone Receptor, negative Estrogen Receptor and Triple-negative breast cancer subgroup." (PMID 34160019, 2021). "Moreover, the existence of the CCL8 gradient, that is, an increasing concentration from neoplastic epithelium via stroma to the periphery, has been reported and found to be a driving force of breast cancer metastasis." (PMID 34885960, 2021). "identify a breast cancer tumor-associated macrophage (TAM) transcriptome that is different from those of monocytes and tissue-resident macrophages, and which is associated with shorter disease-specific survival, and they demonstrate crosstalk between tumor cells and TAMs via SIGLEC1, CCL8, and CSF1." (PMID 30930117, 2019). "In breast cancer, RSAD2, along with HERC5 and CCL8, was identified as a crucial gene impacting prognosis through gene co-expression network analysis." (PMID 40510586, 2025).